CSF1 (colony stimulating factor 1)
Diseases named in the same sentence as CSF1 in open-access papers (continued):
Sharing a sentence is not in itself a finding about the gene and the disease.
tumor (continued). "We utilized the MC38 tumor model to study how systemic inhibition of CSF1 and/or IL34 impacts the tumor microenvironment and growth." (PMID 31552020, 2019). "The MC38 tumor cell line expresses high levels of both cytokines, CSF1 (~900 pg/ml) and IL34 (~300 pg/ml), and thus was utilized to assess macrophage and immune homeostasis in vivo." (PMID 31552020, 2019). "Our analysis suggests that CSF1 primarily drives myeloid cell content within the MC38 tumor microenvironment." (PMID 31552020, 2019). "CSF-1 plays a key role as it also promotes recruited macrophages to adopt M2 phenotype that contributes to tumor invasion." (PMID 31467533, 2019). "On the basis of the scoring, tumor tissues were further sorted into low (scores of 1 and 2; 51.8%) and high (scores of 3 and 4; 48.2%) CSF-1 expression groups." (PMID 31565097, 2019). "Studies have shown that a paracrine loop in CSF-1/CSF-1R signaling between TAMs and tumor cells is required in the tumor microenvironment." (PMID 31565097, 2019). "In general it starts with the production of CSF-1 from the tumor cells which induces EGF production in the TAMs." (PMID 30925924, 2019). "This phenomenon was associated with increased production of TNF, IL-6, CSF-1, VEGF-A, and IL-8 by tumor cells, which contribute to the recruitment of macrophages and the polarization of M2-like macrophages." (PMID 31775797, 2019). "Several mouse tumor cell lines were screened for CSF1 and IL34 secretion in vitro in order to identify a relevant cell used for tumorigenesis and to test CSF1R ligand blockade in vivo." (PMID 31552020, 2019). "CSF-1-induced murine macrophages are thought to exhibit the M2-like polarization state of macrophages, suppressing T cell expansion and promoting tumor growth." (PMID 31438996, 2019). "CSF-1 is produced by macrophages, fibroblasts, and epithelial cells and is also secreted by tumor cells." (PMID 31565097, 2019). "Colony stimulating factor 1 (CSF1) produced by tumor cells contributes to the transformation and differentiation of tumor‐associated macrophages (TAMs) and decreased granulocyte‐specific chemokines in CAFs." (PMID 31365790, 2019). "CAF secretion of CXCL12/SDF1, M-CSF/CSF-1, IL-6, and CCL2/MCP-1 recruits tumor-associated macrophages (TAM) to the TME and actively differentiates TAMs into an M2 immunosuppressive phenotype." (PMID 31058816, 2019). "Cytokines and chemokines derived from tumor cells and cancer-associated fibroblasts (CAFs), such as CSF-1, CXCL12/SDF1, CCL2/MCP-1, CCL5/RANTES, and VEGF, recruit mononuclear cells into the tumor microenvironment and activate them to become TAMs or MDSCs." (PMID 31554173, 2019). "We compared survival and tumor growth of mice treated with anti-CSF1 (selectively TAM depletion), anti-GR-1 (depletion of MDSC), and untreated tumor bearing mice." (PMID 31214202, 2019). "Several clinical trials of CSF-1/CSF-1R inhibitors have been performed or are still open in different tumor types." (PMID 31799182, 2019). "CSF-1 induces macrophage polarization toward an immunosuppressive and M2-like tumour promoting phenotype and it is abundantly expressed by several tumour types." (PMID 31331034, 2019). "Reducing macrophage recruitment into the tumor microenvironment by colony-stimulating factor-1 (CSF-1) blocking antibodies led to an increased abundance of M1 polarized macrophages in the tumor." (PMID 31905723, 2019). "PTEN-deficient sarcomas exhibit enhanced infiltrating myeloid-derived hematopoietic cells, particularly macrophages and neutrophils, recruited via tumor cell-derived CSF-1." (PMID 31775797, 2019). "And the restoration of expression of CSF-1 in CSF-1 null mutant mice with xenografts accelerated both tumor progression and metastasis." (PMID 31300030, 2019). "The induction of interleukin-6 (IL-6), IL-10 and colony stimulating factor 1 (CSF-1) contributes to the proliferation and invasion of tumor cells and thereby displays a pro-tumorigenic role." (PMID 31455032, 2019).
tumor (continued). "An array of tumor-derived chemoattractants such as CSF1, CSF2, CCL2, VEGFA, and SEMA3A contribute to the recruitment of monocytic precursors, resulting in TAMs accumulation." (PMID 31406165, 2019). "For example, the induction of interleukin (IL)-6, IL-10, and CSF-1 contributes to the proliferation and invasion of tumor cells, whereas the secretion of pro-inflammatory IL-1β enhances the antitumor immune response." (PMID 31455032, 2019). "Positive staining expression of CSF-1 predominantly appeared in the nucleus of tumor cells in UTUC tissues." (PMID 31565097, 2019). "Another group showed that pro-inflammatory cytokines TNFα, IL-6, CSF-1, and IFNγ correlated with disseminated tumor cells in BC18." (PMID 30814616, 2019). "On the other hand, TAMs hijack tumor cells into the circulation by a positive feedback loop consisting of tumor cell-produced CSF-1 and TAM-produced EGF." (PMID 31300030, 2019). "Wycoff and colleagues demonstrated how TAMs, usually located at the edge of the tumours, are stimulated by colony stimulating factor 1 (CSF1) to produce epidermal growth factor (EGF), the EGFR natural ligand." (PMID 31554160, 2019). "For example, anti-PD1 treatment combined with anti–angiopoietin-2 or anti-CSF1 antibodies suppresses tumor development in several mouse models." (PMID 31249132, 2019). "In this model, CSF-1/CSF-1R targeting resulted in increased expression of immune checkpoint molecule on tumour cells, including PD-L1 and CTLA-4, thus resulting in only modest increase of CD8+ T cell cytotoxicity." (PMID 31331034, 2019). "TAM cells secrete epidermal growth factor (EGF) and TNF-α, while tumor cells secrete colony-stimulating factor-1 (CSF-1)." (PMID 31192126, 2019). "These TDFs are key mediators in the crosstalk between monocytes and tumor cells and include colony-stimulating factor-1 (CSF-1), several C−C chemokine ligands, such as CCL2, also known as MCP-1 and VEGF." (PMID 31878087, 2019). "Another study reports a short-ranged interaction via EGF/CSF-1 paracrine axis to mediate macrophage-driven tumor cell migration." (PMID 31121840, 2019). "The vascular disrupting agent combretastatin A4-P causes the increased production of CSF-1, CCL2, and CXCL12 that increases monocyte recruitment and TAM accumulation in tumor sites." (PMID 32038607, 2019). "During EMT, tumor cells produce CSF1 which recruits TAMs that are able to produce a diverse array of growth factors, facilitating the formation of a metastatic niche." (PMID 31921140, 2019). "The enhanced anti-tumoral effect of CD8+ T cells as consequence of pharmacological inhibition of CSF-1/CSF-1R axis has also been exploited for combinational therapy with ICBs, especially for tumours resistant to single-agent therapy." (PMID 31331034, 2019). "These novel therapeutic strategies are mainly focused on inhibitors of CSF-1 or CSF-1R alone or combined with other therapeutic agents targeting tumor cells." (PMID 30781344, 2019). "Overexpression of CSF1 in the neoplastic cell population is believed to result in abnormal recruitment of CSF1R-expressing macrophages to the tumor site." (PMID 31906059, 2019). "The data indicated significant associations between disease-free survival and the following two factors: tumor stage (HR = 1.76, CI = 1.01‐3.08, P = 0.046) and CSF-1 expression (HR = 2.14, CI = 1.20‐3.81, P = 0.01) in univariate analysis." (PMID 31565097, 2019). "The CSF-1 expression was primarily localized in the nucleus and was significantly correlated with tumor size (P = 0.04) and patients who had a high stage (P < 0.001), distant metastasis (P = 0.006), recurrence (P = 0.003), and cancer death (P = 0.005)." (PMID 31565097, 2019). "The downstream effects of CSF-1/CSF-1R blockade create an environment with decreased immune suppression and increased interferon response, impeding tumor growth." (PMID 31439034, 2019).
tumor (continued). "Given that bone marrow-derived macrophages (BDMs) are recruited to the tumor by chemokine (C–C motif) ligand 2/CCL receptor 2 (CCL2/CCLR2) or colony-stimulating factor-1 (CSF-1)/CSF-1R axis, inhibitors targeting these ligands and receptors have been developed." (PMID 30823602, 2019). "We show that radiation stimulated the release of colony‐stimulating factor 1 (CSF‐1) by tumour cells." (PMID 30442705, 2018). "Because radiation induced CSF1 in these tumours, we determined the effect of an anti‐CSF1 antibody (aCSF) on TAMs and tumour growth delay after radiation." (PMID 30442705, 2018). "All together, these data strongly suggest that F4/80hi-resident macrophages exposed to high levels of CSF1 (and likely other tumour niche factors) in the tumour microenvironment gain the ability to self-renew within the tumour." (PMID 29422500, 2018). "Tumour infiltration of TAMs is primarily mediated by CSF1, and genetic ablation of CSF1 in mouse models severely limits tumour progression in comparison with wild type mice." (PMID 30577495, 2018). "This paracrine loop involving EGF and CSF1 is crucial for tumor invasion, and the inhibition of either signaling pathway inhibits the migration of both cell types." (PMID 29594035, 2018). "The TKI pexidartinib (PLX3397) blocks the CSF1/CSF1R axis, which inhibits tumor-associated macrophage infiltration along with autocrine and paracrine signaling of CSF1 to inhibit tumor cell growth." (PMID 30450193, 2018). "In keeping with the increased levels of CSF‐1, there was increased infiltration of macrophages in tumours (CD11b+F480+) within 48 h of single‐dose radiation in both MC38 and KPC tumours." (PMID 30442705, 2018). "To confirm that tumor cells express CSF1, we performed ELISA on 3 KPC cell lines and showed high expression." (PMID 29719257, 2018). "We find that a soluble factor produced by tumor cells is responsible for macrophage RAE-1δ induction, and we identify tumor-derived colony-stimulating factor-1 (CSF-1) as necessary and sufficient for macrophage RAE-1δ induction in vitro and in vivo." (PMID 29757143, 2018). "Our recently published study identified a new Kindlin-2/TGFβ/CSF-1 signalling axis that BC cells utilize to recruit and polarize host macrophage to drive tumour progression." (PMID 29743493, 2018). "Others have also shown that Flt3L treatment or colony-stimulating factor 1 (CSF1) neutralization expands cDC1 numbers in the tumor and increases response to both chemotherapies and immunotherapies." (PMID 29593283, 2018). "Accordingly, the inhibition of CSF-1 or EGF signaling in tumor-bearing mice undergoing intravital imaging experiments reduced metastasis by decreasing the number of macrophages and tumor cells able to leave the primary tumor." (PMID 30200242, 2018). "This macrophage-mediated motility centres around two paracrine signalling loops, comprised of TAM-expressed EGF and tumour-derived CSF1." (PMID 30577495, 2018). "For instance, the induction of interleukin-6 (IL-6), IL-10, and colony stimulating factor 1 (CSF-1) contributes to the proliferation and invasion of tumor cells and thereby displays a pro-tumorigenic role." (PMID 30115069, 2018). "Chemotaxis-based experiments and intravital imaging revealed that reciprocal signaling between tumor cell-derived CSF-1 and TAM-derived EGF is essential for the promotion of tumor cell migration." (PMID 30356678, 2018). "This work also confirmed the involvement of the EGF and CSF-1 paracrine loop in tumor cell migratory streaming by using erlotinib to block the EGFR on tumor cells or by using CSF1R antibodies to block the CSF1R on macrophages." (PMID 29599778, 2018). "CSF1 blockade decreased M2 tumour infiltration in vivo and reprogrammed resident TAMs to an inflammatory phenotype." (PMID 30577495, 2018). "Tumor-derived factors such as C-C ligand 2 (CCL2) and colony stimulating factor-1 (CSF-1) can also recruit further macrophages to the tumor from the bone marrow (BM) and spleen." (PMID 30459812, 2018).
tumor (continued). "Bone marrow-derived monocytes (F4/80low) are recruited to the tumour via secretion of CSF1 and monocyte chemoattractant protein 1 (MCP1 or CCL2)." (PMID 30577495, 2018). "Macrophage recruitment was promoted by radiation‐induced upregulation of CSF‐1 by tumour cells and was reversed by the administration of anti‐CSF antibody (aCSF)." (PMID 30442705, 2018). "CSF1 is certainly a key component of the tumour niche to manipulate macrophage self-renewal, but other cues can also contribute to this process and, therefore, reconstruction of the tumour niche would be very illuminating." (PMID 29422500, 2018). "We used ELISA to analyze CSF-1 protein levels in tumor microenvironments in vivo from mechanically dissociated S.C. tumors and found the concentrations of intratumoral CSF-1 were much greater in B16 tumors than in RMA-S tumors." (PMID 29757143, 2018). "We find here that induction RAE-1δ on TAMs occurred in tumor microenvironments containing high levels of CSF-1." (PMID 29757143, 2018). "Tissue samples from KPC mice and patients with PDAC were further stained with immunofluorescence antibodies to evaluate the presence of CSF1R ligands, CSF1, and interleukin-34 (IL-34) in the tumor microenvironment." (PMID 29719257, 2018). "Preventing recruitment of macrophages to the tumor site has been achieved through targeting macrophage chemoattractants such as CSF-1 and CCL2 or their corresponding receptors: CSF-1 receptor (CSF-1R) and C-C chemokine receptor type 2 (CCR2)." (PMID 30356656, 2018). "Unexpectedly, we find that the cytokine colony-stimulating factor-1 (CSF-1) is released by tumor cells and is necessary and sufficient to induce RAE-1δ at the mRNA and cell surface levels on macrophages in vitro and on tumor-associated macrophages in vivo." (PMID 29757143, 2018). "CSF1 silencing in tumor cells reduces host macrophage invasion, angiogenic activity, and tumor xenograft growth in mice." (PMID 30237497, 2018). "CSF1 recruits macrophages to the tumor site on the one hand and CSF-1-educated TAMs have a central role in supporting tumor cell survival, proliferation, motility and in suppressing anti-tumor immunity on the other." (PMID 29796177, 2018). "TAMs have been shown to engage in a CSF1-EGF paracrine signaling loop capable of leading tumor cells to the invasive edge of a tumor." (PMID 29946544, 2018). "Here the authors show that in the colon these macrophages are CCR2-dependent, while in tumours they gain the ability to self-renew, relying on CSF1 and promoting cancer progression." (PMID 29422500, 2018). "This work indicated that maintaining an EGF and CSF-1 paracrine loop between tumor cells and TAMs was required for the migration of breast tumor cells to the surrounding tissue and blood vessels." (PMID 29599778, 2018). "Co-localization indicated that pancreatic epithelial tumor cells produce both CSF1 and IL-34 in mouse and human." (PMID 29719257, 2018). "Collectively, miR-125b abundance in tumor cells determines TAM recruitment at least partly by regulating chemokine CSF1 and CX3CL1 directly and/or indirectly." (PMID 30237497, 2018). "For example, macrophage ablation in the PyMT mice by genetic deletion of colony stimulating factor 1 (CSF1) suppresses tumor angiogenesis and pulmonary metastasis of cancer cells." (PMID 30483271, 2018). "In vivo, serum from mice bearing KPC tumours had elevated CSF‐1 compared to naïve mice, whilst serum CSF‐1 in mice bearing MC38 tumours was not elevated." (PMID 30442705, 2018). "TAMs occupy 50% of the tumor volume and provides paracrine signals via CSF-1/CSF-1R axis, which promotes tumor progression." (PMID 30352606, 2018). "Our study suggests that miR-125b in tumor cells regulates the production of CSF1 and CX3CL1 for recruiting macrophages to the neoplastic sites." (PMID 30237497, 2018). "IL-6 and CSF-1 also induce mTOR activation, resulting in cell survival and growth of alternatively activated macrophages in the tumor microenvironment." (PMID 29422647, 2018).
tumor (continued). "Patient tissues were stained with antibodies against CD68 for macrophages, pan-cytokeratin for epithelial tumor cells, and with either CSF1 or IL-34." (PMID 29719257, 2018). "Monocytes are recruited to sites of tumor growth in response to chemoattractants released by tumor cells, such as colony stimulating factor 1 and the chemokine C-C motif chemokine ligand 2 (CCL2), where they differentiate into macrophages." (PMID 29765907, 2018). "Coincident with the elevation in CSF‐1, macrophages increased in tumours, peaking 5 days following irradiation." (PMID 30442705, 2018). "Many studies have demonstrated a relationship between the abnormal expression of CSF-1/CSF-1R and tumor development." (PMID 29228668, 2017). "Colony stimulating factor-1 (CSF-1) is abundantly expressed by many tumor cells and their stromal cells in TME." (PMID 28694739, 2017). "Neoplastic cells and tumor-associated macrophages (TAM) secrete IL-6, CSF-1, IL-10, TGF-β, TNF-α, IL-1α, angiogenic and lymphangiogenic growth factors that promote tumor development." (PMID 28830415, 2017). "An important EGFR/CSF-1R paracrine loop exists between macrophages and tumor cells in which CSF-1, produced by carcinoma cells and bound by macrophages, promotes the proliferation, differentiation, and polarization of macrophages toward an M2-like phenotype." (PMID 28955335, 2017). "Upregulation of CSF1 has been demonstrated to facilitate tumor invasion and contribute to CSC-like properties in HCC." (PMID 28445151, 2017). "Neutralizing antibodies to GM-CSF, G-CSF and CSF-1 have shown abilities to inhibit tumor growth in mice, including pancreatic cancer, colon cancer and lung cancer, by inhibition of proliferations of MDSCs and TAMs." (PMID 28694739, 2017). "The inhibition of CCL2/C–C chemokine receptor type 2 or CSF1/CSF1-R pathways by several methods was shown to efficiently induce tumor regression." (PMID 28769933, 2017). "Mechanistically, tumour cells secrete CSF1, which stimulates macrophages to produce EGF that in turn activates migration of the tumour cells." (PMID 29065107, 2017). "At the same time, tumor cells secrete colony-stimulating factor-1 (CSF-1) which in turn promote the expression of EGF by macrophages." (PMID 28970798, 2017). "It has been shown that the colony-stimulating factor-1 (CSF-1) and its receptor CSF-1R sustain monocytes/macrophages survival, proliferation, and motility, and also contribute to tumor progression." (PMID 28170411, 2017). "A paracrine interaction between CSF-1-secreting tumor cells and epidermal growth factor (EGF)-secreting TAMs stimulates relay chemotaxis through direct cell-cell contact, leading to invasion of both cell types together towards blood vessels." (PMID 28629162, 2017). "In an experimental model, inhibition of M-CSFR signaling impaired the extravasation and recruitment of monocytes into the tumor, whereas overexpression of CSF-1 in wild-type mice accelerated tumor progression." (PMID 28220123, 2017). "We observed a significant threefold increase in tumor cell death in the anti‐CSF1 and chemotherapy combined treatment compared to chemotherapeutic treatment alone." (PMID 29038312, 2017). "Macrophages flocked to the tumour, the so-called tumour-associated macrophages (TAMs), are generally recruited by the activation of CSF1R by CSF-1 or IL-34, as well as by the chemokine CCL2." (PMID 28404796, 2017). "EGF also stimulates the secretion of CSF-1 by tumor cells, thereby forming a positive feedback loop between tumor cells and macrophages." (PMID 28955335, 2017). "Myeloid-derived autophagy also plays a critical role in impairing antitumor immune responses and promoting the survival and accumulation of M2 macrophages in tumor tissues in a CSF-1 and TGF-β-dependent manner." (PMID 28686632, 2017). "From a mechanistic perspective, MMP2, MMP12 and VEGFA, which are produced by macrophages and are important in tumor invasion and angiogenesis, are downregulated upon blockade of the CSF1/ CSF1R axis." (PMID 28467800, 2017).